IDH1 (isocitrate dehydrogenase (NADP(+)) 1)
Diseases named in the same sentence as IDH1 in open-access papers (continued):
Sharing a sentence is not in itself a finding about the gene and the disease.
glioma (continued). "However, as of 2016, phenotypic and genomic characteristics of gliomas, such as isocitrate dehydrogenase 1/2 (IDH1/2) mutation status and co-deletion of 1p/19q chromosomal regions, have been incorporated into classification, grading, prognosis, and determination of response to therapy." (PMID 38561856, 2024). "The use of DL in neuropathology, particularly the development of an image-based prediction of molecular driver workflow (e.g., IDH1/2 mutation status or CDKN2A/B copy number status in low-grade gliomas), may provide accessible tools for pathology labs with limited access to molecular testing." (PMID 38893099, 2024). "Epigenetics is associated with DNA methylation, and the IDH1 gene induces demethylation;18 therefore, epigenetic regulation of the IDH1 gene becomes a key biomarker for tumor classification and plays a critical role in the evolution and biological expression of gliomas." (PMID 37354775, 2023). "Also, ADC values were significantly higher in IDH1‐mutated gliomas than in IDH1‐wild‐type gliomas." (PMID 36866773, 2023). "For instance, the granulocyte colony-stimulating factor secreted by mutated IDH1 glioma could enhance the efficacy of immunotherapy for patients with LGG by reprogramming the tumor microenvironment and promoting the generation of non-immunosuppressive myeloid cells." (PMID 37153540, 2023). "Notably, all of the 1p/19q codel and GCIMP-high gliomas are mutated in IDH1 or IDH2." (PMID 37372972, 2023). "However, the molecular mechanisms that mediate increased survival in glioma patients carrying IDH1 mutations remain unknown." (PMID 37952042, 2023). "IDH1 missense mutations are related to low-grade gliomas and may bring patients better prognoses." (PMID 37114036, 2023). "A study suggests that targeting pyrimidine metabolism reprogramming in cancer stem cells and lower expression of pyrimidine metabolism indicates a better prognosis of glioblastoma, and pharmacologic inhibition of glutathione metabolism could be valuable for patients with IDH1-mutated glioma." (PMID 36033510, 2022). "Thus, the aim of this study was to analyze the methylation level of the ABCB1 promoter in glioma patients of different WHO grades to establish its utility as a potential biomarker based on its relation to the IDH1 mutation status and other clinicopathological data." (PMID 36233525, 2022). "Moreover, to confirm the link between the number of peritumoral neutrophils and the greater biological aggressiveness of gliomas, patients with IDH-1 wild-type glioma, which is mostly associated with a poorer prognosis, have higher peritumoral neutrophil levels than low-grade, IDH1-mutated gliomas." (PMID 35741816, 2022). "In addition, much like the histone mutations, IDH1/2 mutated gliomas also exhibit broad disruptions in chromatin modifications including DNA methylation and histone methylation (H3K9me2, H3K27me2, H3K79me2), which ultimately results in a failure in differentiation." (PMID 36686810, 2022). "Therefore, DDR score seemed to be a robust indicator of IDH1 mutation status in glioma." (PMID 35720326, 2022). "Importantly, IDH1 mutation confers a distinctive survival advantage in glioma patients; large cohort studies confirmed a 2-fold increase of median overall survival in glioblastoma patients and a more than threefold increase in lower-grade glioma patients compared with their respective controls." (PMID 35501312, 2022). "Hence, gliomas with IDH1 mutation are characterized by slower tumor progression." (PMID 36289655, 2022). "Moreover, IDH1 mutations were shown to alter redox metabolism in glioma cells." (PMID 35628596, 2022). "Moreover, 63 and 64 inhibited BT142 glioma cells bearing IDH1 R132H mutations." (PMID 35786935, 2022).
glioma (continued). "Noteworthily, demethylation-inhibiting IDH1 mutation increases the DNA 6mA content in human gliomas, but the depletion of the demethylase candidate ALKBH1 fails to do so, together suggesting the presence of other unknown 6mA demethylase for erasing misincorporated DNA 6mA." (PMID 35501312, 2022). "Therefore, IVIM-DWI might be a promising method to predict IDH1 gene mutation and evaluation of gliomas peritumoral diffusion." (PMID 33795525, 2021). "In addition, the assay may have utility in other genetic mutations, such as IDH1/2 mutations in gliomas, and genetic makers can improve clinical targeted therapy development." (PMID 34159191, 2021). "In addition, the high rate of IDH1 mutation on TrE in our data may be due to the radiosensitization and a less aggressive phenotype of IDH1 mutated gliomas." (PMID 34059015, 2021). "Interestingly, one study showed that combined analysis of IDH1/2 and pTERT mutational status could be used to distinguish if a glial lesion is glioma or reactive glioma." (PMID 33547950, 2021). "Additionally, somatic mutations in KMT2C (FDR = 0.046) and CDH1 (FDR = 0.045) were found to be significantly associated with later-onset BRCA, while those in EGFR (FDR = 1.34E-7) and IDH1 (FDR = 1.34E-7) were found to be significantly associated with later-onset gliomas." (PMID 34788626, 2021). "Univariate regression analysis results showed that PACSIN1 (p < 0.0001), with all clinical indicators including age (p < 0.0001), IDH1 mutation status (p < 0.0001), 1P/19q codeletion status (p < 0.0001), and grade (p < 0.0001) could be used as a predictor of OS of gliomas at all grades." (PMID 34422904, 2021). "The results showed that BCAT1 is increasingly expressed in glioma tissues corresponding to increasing tumor grade, and compared to IDH1 wild-type diffuse glioma patients, the patients that had gained IDH1 R132H mutation showed a lower percentage of tumor cells with detectable BCAT1 expression." (PMID 33493139, 2021). "Furthermore, Cox proportional hazards regression was performed to investigate the predictive value of hippocampal volume, considering that histological grade (III, IV), age, IDH1 status, and contrast-enhancing volume are associated with OS in patients with high- grade glioma." (PMID 32507763, 2020). "Indeed, previous studies have shown that gliomas with IDH1 mutation had a better response to treatment with chemotherapeutic agent temozolomide, indicating the role of IDH1 mutation as a predictive marker." (PMID 32856857, 2020). "IDH1 mutations caused down-regulation of leukocyte chemotaxis, resulting in reduced immune infiltrates that may contribute, in part, to differences in the aggressiveness of mutant type gliomas." (PMID 33228738, 2020). "However, the function of the small GTPase family in lower-grade gliomas, especially IDH1-mutated gliomas, is mostly unknown." (PMID 32224866, 2020). "Notably, 22.7% of adult NTRK-fused gliomas in our cohort are IDH1 p.R132H mutated, raising questions about the oncogenic driver event in these specific tumors and whether they display oncogenic dependence on the NTRK fusion." (PMID 32665022, 2020). "As the earliest detectable genetic alteration in gliomagenesis, IDH1 heterozygous missense mutations in codon 132 cause an arginine-to-histidine substitution in 80–90 % of cases (R132H) that leads to a distinct metabolism and hypermethylation phenotype in gliomas." (PMID 32003759, 2020). "Importantly, the IDH1R132H mutation influenced the expression of the NAD-synthesis-associated enzyme NAMPT differently in the glioma cells and astrocytes, supporting the hypothesis that the IDH1 mutation differentially affects cells during tumorigenesis." (PMID 31888244, 2019). "Therefore, IDH1/2 mutations block glioma stem cell differentiation." (PMID 31263678, 2019).
glioma (continued). "In addition to the further increase in the ratio of 2-HG/tCho, we found a significantly higher metabolite ratio of myo-Inositol/tCho in IDH2 gliomas (four patients with IDH2 R172K and one patient with IDH2 R172W mutations) compared to IDH1 gliomas (fifteen patients with IDH1 R132H mutation)." (PMID 30791611, 2019). "Different strategies to suppress the expression or activity of mutated IDH1 or to inhibit the production of 2-hydroxyglutarate with metabolites such as oxaloacetate have been evaluated in vitro and in clinical trials including a currently performed phase-I trial on gliomas." (PMID 31200581, 2019). "Understanding malignant progression in IDH1 mt and wt patients at multiple scales and in a spatial context is pivotal to delineating biological events underlying glial tumors and may facilitate tailored treatment approaches as well as reveal new therapeutic targets." (PMID 31881020, 2019). "Thus, we have uncovered a mechanism by which tumor cell survival may be promoted in conditions associated with perturbed redox homeostasis, as occurs in IDH1-mutated glioma." (PMID 29562167, 2018). "Besides the combination approach being investigated, IDH1/2 mutant gliomas associated with 2-hydroxygluterate (2HG)-mediated homologous recombination (HR) defect may potentially benefit from PARPI monotherapy." (PMID 30723695, 2018). "However, collectively, the in vitro and in vivo data, therefore, suggest that PYCR1 may play a role in redox regulation in IDH1-mutated gliomas." (PMID 29562167, 2018). "Therefore, we used glioma stem cells (GSC) maintaining the ability to differentiate into cells expressing markers of all three neural lineages to study neuronal differentiation of glioma cells and its association with IDH1 mutations, outcome, and epileptic seizures." (PMID 30297697, 2018). "Similarly, Prof. Lu also presented several case studies for radiomics research, focused on the prediction of glioma survival, prediction of mutations in the gene encoding isocitrate dehydrogenase 1 (IDH1), prediction of glioma pseudoprogression, as well as glioma radiation genomics, respectively." (PMID 28797870, 2017). "Also with the majority of these favourable glioma expressing an IDH1 mutation, tracers targeting this protein may provide more specific determination of target volume to potentially reduce extent of CTV." (PMID 28253929, 2017). "In addition, glioma subtypes can be identified by the IDH1/IDH2 mutation." (PMID 28851427, 2017). "In addition, increased expression of RAD50 interactor 1 (RINT1) and isocitrate dehydrogenase 1 (IDH1) R132H may represent risk factors for low-grade glioma-related seizures." (PMID 29212163, 2017). "Identification of somatic mutations in the key Krebs cycle enzymes, namely, the IDH1/2 in low-grade gliomas (astrocytomas, oligodendrogliomas, oligoastrocytomas) and secondary glioblastomas, but not in primary glioblastomas has been a recent focal point in glioma biology." (PMID 28346397, 2017). "Cancer-associated IDH1/2 mutations lead to the loss of the enzyme’s normal catalytic activity and gain neomorphic activity of reducing αKG to (R)-2-hydroxyglutarate (2-HG), which can be detected at high levels in gliomas and AML patients harboring these mutations." (PMID 29184081, 2017). "Thus, the mechanism of IDH1 mutation sensitivity to chemotherapy should be further researched and people should provide new ideas to promote IDH1 mutation inhibitors exploration and glioma treatment." (PMID 28427200, 2017). "Furthermore, mTOR signalling is readily observed in clinical samples of IDH1-mutated gliomas." (PMID 27624942, 2016). "In addition, the vast majority of the gliomas with IDH1 mutation were found in the RMPAlow subtype." (PMID 27385209, 2016). "Moreover, mutations in IDH1 occurring at arginine 100 (R100), which may also be pathogenic have also been identified in gliomas." (PMID 26948489, 2015).
glioma (continued). "Also, mutated IDH1 has been reported as a marker indicating that more radical surgical glioma resection may be of benefit for the patient." (PMID 25720744, 2015). "However, in contrast to the two previous meta-analyses, the present meta-analysis included 55 independent publications, with 9487 glioma cases, which should meaningfully increase the statistical power and accurately estimate the effect of IDH1/2 mutations on the prognosis of patients with glioma." (PMID 26220714, 2015). "In spite of the limited number of cases with combined IDH1 mutation and 11p deletion, it would be interesting to explore this finding in larger cohorts given the importance of IDH1 mutations in some of the emerging subtype classification systems developed for glioma." (PMID 25953855, 2015). "Finally, polySia expression associated with one of the key features in gliomas, IDH1 mutation." (PMID 25164322, 2014). "However, IDH1 mutation reduced the invasion ability of glioma cells." (PMID 24520288, 2014). "This may partly explain why glioma patients with mutated IDH1 have a longer survival period." (PMID 24520288, 2014). "However, the effects of IDH1 mutation on the biological behavior of glioma cells and the associated mechanisms, as well as the possible effects they may have on clinical therapy, have not been studied." (PMID 24520288, 2014). "Mutated IDH1 and increased 2-HG may therefore pre-dispose glioma cells to DNA hypermethylation." (PMID 24716189, 2014). "In spite of all the studies, the role of IDH1 mutation in the recurrence of gliomas is unknown." (PMID 23840696, 2013). "In addition, by analysing other known clinical prognostic factors for high-grade glioma, we found that besides the miRNA signature identified (P = 7.36e-6), IDH1 mutation status was also associated with the survival of high-grade glioma patients in univariate analysis (P = 0.026)." (PMID 24194606, 2013). "The oligodendroglioma model presented here is a valuable model for further functional elucidation of the effects of IDH1 mutations on tumor metabolism and may aid in the rational development of novel therapeutic strategies for the large subgroup of gliomas carrying IDH1 mutations." (PMID 24252742, 2013). "However, the detection of divertive tumor cell clones in morphological distinct tumor components sharing IDH1- mutations as early event may provide insight into the tumorigenesis of true mixed gliomas." (PMID 22844452, 2012). "Nevertheless, the existence of exclusively heterozygous IDH2 (and IDH1) mutations in gliomas and AML and the small possibility of dominant-negative mutations (minor mutant fractions existing could not exert this role) have led to the search for other consequences of IDH1 and IDH2 mutations." (PMID 22675360, 2012). "Thus, future studies are warranted to confirm or disprove our observation of wild type reversion of IDH1 in recurrent gliomas that harbored IDH1- mutations in their primary tumor, to fully understand its importance for tumor maintenance and during tumor progression." (PMID 22844452, 2012). "If altered IDH1- enzyme activity or the novel enzymatic product 2-hydroxyglutarate due to the mutation directly set the stage for an increased chromosomal and genetic instability of affected gliomas facilitating additional molecular events remains to be elucidated." (PMID 22844452, 2012). "Moreover, IDH1 mutation is probably the earliest stage of glioma tumourigenesis." (PMID 21326241, 2011). "Their result is in agreement with our own; the normalised difference between glioma and brain T values (e.g., ΔT) exhibits strong potential as an IDH1 biomarker." (PMID 41436375, 2026). "Determining IDH1 status of glioma is an important step in identifying tumour severity and will inform treatment course for the patient." (PMID 41436375, 2026).
glioma (continued). "We found that a measurement of tumour T normalised to the brain (ΔT) was capable of distinguishing IDH1‐mutant and ‐wild‐type glioma across a wide range of spin‐lock frequencies." (PMID 41436375, 2026). "Impairment was substantially less prevalent lower compared to IDH-1 wildtype glioma, in line with previous studies." (PMID 41514682, 2026). "In co-culture assays, IDH1-mutant glioma cells and their GCM suppressed PD-1 and CTLA-4 expression on ILCs while promoting proliferation." (PMID 41917320, 2026). "IDH-mutant gliomas can be classified as having the CpG island methylator phenotype (G-CIMP), which is characterized by widespread epigenetic changes associated with IDH1 mutations." (PMID 41749891, 2026). "The metric ΔT, which normalises tumour T to healthy brain tissue, captures the distinction between IDH1‐mutant and ‐wild‐type glioma cases." (PMID 41436375, 2026). "Mice bearing IDH1‐mutant and ‐wild‐type glioma underwent quantitative T1ρ imaging over the course of tumour development." (PMID 41436375, 2026). "It was found that IDH1‐mutant gliomas exhibited significantly higher T values in the tumour compared with the brain, while IDH1‐wild‐type gliomas presented similar T values in the tumour and brain." (PMID 41436375, 2026). "IDH1‐wild‐type glioma exhibits little difference in tumour and brain T values (ΔT), while IDH1‐mutant tumours present significantly higher T values in tumour than brain (ΔT)." (PMID 41436375, 2026). "A measurement of tumour T normalised to the brain (ΔT) was able to distinguish between IDH1‐mutant and ‐wild‐type glioma, with IDH1‐mutant mice exhibiting an average ΔT of ∼29% and IDH1‐wild‐type mice having an average ΔT of only ∼3%." (PMID 41436375, 2026). "This study consisted of three groups of five mice: naïve controls, IDH1‐wild‐type glioma bearing and IDH1‐mutant glioma bearing, imaged once weekly with a T‐prepped EPI sequence." (PMID 41436375, 2026). "Tonsil-derived human ILCs were co-cultured with IDH1-mutant or wild-type glioma cells and their GCM." (PMID 41917320, 2026). "Both GBM and IDH1‐mutant gliomas exhibited pronounced variability, reflecting diverse immune landscapes within spatially distinct regions." (PMID 41249878, 2026). "Patient-derived glioma neurosphere lines (MGG119, TS603S2, BT142, and MGG152) were studied, with IDH1-mutant fibrosarcoma HT1080 and an inducible IDH1-R132H glioma line (MGG18 Tet±)." (PMID 41908147, 2026). "In particular, we evaluate T relaxation time and T dispersion in a mouse model, comparing IDH1‐mutant and ‐wild‐type glioma‐bearing mice, as well as naïve controls." (PMID 41436375, 2026). "An ongoing trial (NCT05669339) combines vorasidenib with pembrolizumab for recurrent IDH1-mutant gliomas, including grade 4 cases, but data are pending." (PMID 40657255, 2025). "Studies have discovered that IDH1 mutant glioma cells respond to medications that target enzymes in the de novo pyrimidine nucleotide synthesis pathway, providing new therapeutic options for patients with IDH mutations, which are common in gliomas." (PMID 40519301, 2025). "We input the feature sequence extracted by the feature extractor into the CRNN classifier for glioma grading, IDH1 classification and pituitary tumor classification." (PMID 40127071, 2025).